CXCL12 (C-X-C motif chemokine ligand 12)
Diseases named in the same sentence as CXCL12 in open-access papers (continued):
Sharing a sentence is not in itself a finding about the gene and the disease.
tumor (continued). "In addition, re-expression of functional, endogeneous CXCL12 in CRC cells was shown to reduce metastatic tumor formation significantly while silencing CXCL12 greatly enhanced the metastatic potential of CRC cells." (PMID 21349176, 2011). "The importance of the CXCL12/CXCR4 axis in tumor progression and metastasis has been emphasized." (PMID 21349176, 2011). "Similarly, blocking of its receptor, CXCR4, resulted in reduced migration of MCs further, strengthening the notion that a CXCL12/CXCR4 axis plays an active role in MC recruitment to the tumor site." (PMID 21949886, 2011). "Thus, the intracellular signaling involved in CXCL12 tumor cell proliferation is extremely dependent on the cell type analyzed." (PMID 20049170, 2010). "Therapies that boost CXCL12 levels at the primary tumor site may prove more effective in the treatment of metastatic breast cancer." (PMID 20849618, 2010). "However, CXCL12 was found not only in tumour cells, but also in endothelial and stromal cells, and overall expression in the entire tissue compartment is more difficult to assess by immunohistochemistry." (PMID 20386750, 2010). "Differential expression of CXCL12 was confirmed by RT-PCR and correlated with local tumour growth." (PMID 20386750, 2010). "Moreover, the anti-tumor effect of CXCL12 was reduced in pfp-/- mice, which lack the cytotoxic mediator perforin, and TRAIL-/- mice." (PMID 20849618, 2010). "Given that CXCL12 induces responses in a variety of leukocytes, we sought to determine whether CXCL12 was affecting the anti-tumor immune response." (PMID 20849618, 2010). "Moreover, coculture experiments, using HPMCs and EOC, showed a strong increase in CXCL12 release, suggesting that some tumor-derived factors upregulate CXCL12 levels in ascites." (PMID 20049170, 2010). "The regulation of CXCR4 surface expression by 5T4 molecules may provide a new way to control response to the chemokine CXCL12 in normal circumstances but could be selected to advantage the spread of a tumor from its primary site." (PMID 20376365, 2010). "CXCL12 can induce different responses depending on the tumor type." (PMID 20849618, 2010). "Importantly, expression of chemokine (C-X-C motif) ligand 12 (Cxcl12) which plays an essential role in tumour migration remained downregulated." (PMID 21152443, 2010). "CXCL12 plays a well-recognized role in the process of tumor progression." (PMID 20380740, 2010). "In contrast to CXCL12(P2G), wild-type CXCL12 inhibited both metastasis and primary tumor growth." (PMID 20849618, 2010). "IFN-γ is important for the inhibition of 4T1.2 tumor growth mediated by CXCL12." (PMID 20849618, 2010). "The levels of CXCL12 at the tumor site may determine the type of immune response generated, with lower levels promoting the accumulation of immunosuppressive cells while higher levels recruit immunoresponsive cells." (PMID 20849618, 2010). "Migration of CXCL12(P2G)-expressing 4T12P2G cells to the lungs was also inhibited when the tumor cells were introduced directly into the circulation, suggesting that CXCL12(P2G) interferes with steps of metastasis that occur after metastatic cells have escaped from the primary tumor." (PMID 20849618, 2010). "As CXCL12 is abundantly expressed by stromal cells, this could be an exemplary example for the role of tumour microenvironment interaction in modulating the therapeutic response." (PMID 21045835, 2010). "Correlation of CXCL12-expression in tumour cells with clinicopathological patient characteristics." (PMID 20386750, 2010). "In addition, 4T1.2 cells were transfected with a construct encoding wild-type CXCL12, to determine the effect of wild-type CXCL12 on tumor growth and metastasis." (PMID 20849618, 2010). "The ability of CXCL12 to enhance the survival of mature DC may be critical to the generation of sufficient mature DC for priming of anti-tumor T cells and may represent a key aspect of the anti-tumor response." (PMID 20849618, 2010).
tumor (continued). "The interaction of CXCR4 and CXCL12 may promote tumor progression and metastasis via the induction of VEGF-mediated angiogenesis." (PMID 20953377, 2010). "These signaling molecules could serve as key messengers between the tumor and its microenvironment, as shown for CXCL12 and CXCL14, which are overexpressed in tumor-associated myoepithelial cells and myofibroblasts." (PMID 19187537, 2009). "All the changes described occur before detection of CXCL-12 in the tumor stroma." (PMID 19226458, 2009). "Results of immunohistochemical staining showed that both nerves and tumor cells expressed CXCL12." (PMID 18983683, 2008). "Thirdly, CXCL12 promotes tumor cell adhesion to the basement membrane components." (PMID 18983683, 2008). "Furthermore, The previous views suggested that tumor cells express high CXCR4 and the metastasis-targeted organs express high CXCL12, so the tumor cells were attracted to the ligand in these organs." (PMID 18983683, 2008). "Some research validated that tumor cells can also express CXCL12." (PMID 18983683, 2008). "Among the family of chemokines and their receptors that significantly contribute to the initiation, progression, invasion and metastasis of tumors, tumor cells expressing high CXCR4 are often found in tissue expressing CXCL12, perhaps due to organ-specific metastasis." (PMID 18983683, 2008). "There has recently been an overwhelming amount of evidence suggesting that the CXCR4/CXCL12 chemokine signaling axis may play an integral role in the metastatic progression of many tumor types." (PMID 18001467, 2007). "In contrast, the high levels of CXCL12 detected in the adrenal glands and liver, may be related to the increased primary NB tumour and secondary metastatic growth in these tissues." (PMID 17925864, 2007). "To collect evidence whether CXCL12 may be a factor relevant to tumour growth in vivo, we measured the concentration of CXCL12 in the primary and secondary tumours as well as in selected host tissues." (PMID 17925864, 2007). "It seems that CXCL12 counteracts carcinogenesis acting as a tumour-suppressor gene like molecule." (PMID 11953881, 2002). "Therefore, CXCL12 seems to be a promising molecule useful for the presensibilisation of tumour cells in a combination-therapy of RCC." (PMID 11953881, 2002). "Consequently, we hypothesized that the temporal elevation of CXCR4 expression in tumor‐infiltrated CD8+ T cells promotes their migration toward CXCL12‐expressing CAFs." (PMID 41257391, 2026). "Upstream, tumor-stromal interactions may contribute to PDIA6 upregulation, as cancer-associated fibroblast-derived C-X-C motif chemokine ligand 12 (CXCL12) activated C-X-C chemokine receptor 4 (CXCR4)-dependent signal transducer and activator of transcription 3 (STAT3) signaling in vitro." (PMID 42234404, 2026). "Moreover, cellular components such as cancer-associated fibroblasts (CAFs), tumor-associated macrophages (TAMs), and regulatory T cells (Tregs) drive immune evasion and therapeutic resistance via cytokine signaling axes, including IL-6/STAT3 and CXCL12/CXCR4." (PMID 42294061, 2026). "Finally, cancer-associated fibroblasts (CAFs), identified by their high expression of CAF markers, interacted with EPCs and CD34+ Pro-B cells via CXCL12/CXCR4, promoting tumor progression and angiogenesis, as found in many tumor studies where CAFs promote tumor invasion via CXCL12/CXCR." (PMID 40990011, 2025). "Additionally, tumor heterogeneity and compensatory signaling pathways may limit the efficacy of CXCL12-targeted therapies, necessitating further investigation into combination strategies with other immunotherapies or targeted treatments." (PMID 40481962, 2025). "In this environment, CXCL12, secreted by cancer-associated fibroblasts (CAFs) and mesenchymal stem cells, binds to the CXCR4 protein expressed on TNBC cells and immune cells, leading to the activation of signalling pathways, which promote an immunosuppressive tumour environment." (PMID 41002447, 2025).
tumor (continued). "Finally, we examined whether elevated TGFβ1 and CXCL12 levels mediate the tumor‐promoting effects of exosomal CMTM4 in OC." (PMID 40433989, 2025). "TCGA data confirmed that CXCL12 and SPHK1 expression correlated in COAD tumor samples, but not in normal colon tissue, suggesting that ramping up CXCL12 and S1P production by cancer cells in the tumor microenvironment may be one strategy used by cancer cells for tumor progression." (PMID 40155684, 2025). "Interestingly, SPHK1 and CXCL12 expression also positively correlated in COAD tumor samples." (PMID 40155684, 2025). "In addition to CXCL13 involved in inducing the formation of TLSs, CXCL12 was also found to be closely related to the formation of TLSs, and the expression of CXCL12 features could effectively promote the enrichment of TLSs in the tumor microenvironment." (PMID 40612858, 2025). "Moreover, gene-environment interactions—such as regional variations in CXCL12 gene polymorphisms, H. pylori infection, EBV prevalence, and lifestyle factors—may affect chemokine expression and tumor behavior." (PMID 40481962, 2025). "In addition, the subgroup analysis showed that the association between tumor expression of CXCL12 and OS was not significantly affected by the mean age and the proportion of men of the included patients (p for subgroup difference = 0.58 and 0.32)." (PMID 40481962, 2025). "Additionally, it has been demonstrated that Hg (methylmercury) might influence the tumor microenvironment by modulating the secretion of CXCL12, the ligand for CXCR4, in the cerebrum of the 129/Sv mice." (PMID 40362664, 2025). "The publication bias underlying the meta-analysis for the association between tumor expression of CXCL12 and PFS could not be determined because only two studies were available." (PMID 40481962, 2025). "In addition, CAFs have been shown that CAFs may directly stimulate tumor angiogenesis via paracrine CXCL12 signaling in GC." (PMID 40485724, 2025). "Fourth, appropriate PET radiopharmaceuticals need to be selected for tumor imaging (FDG or Ga-68-FAPI (fibroblast activating protein inhibitor) targeting cancer associated fibroblasts) and inflammation imaging (FDG or Ga-68-Pentixafor targeting chemokine signals (CXCL12/CXCR4 pathway), respectively." (PMID 40612332, 2025). "However, the mechanism of primary tumor-induced CXCL12 expression in the peritumor intestine remains unknown." (PMID 40756343, 2025). "In addition, MSCs-derived CXCL12 can induce BMDMs to transform into M2 phenotype, thus forming an immunosuppressive microenvironment that enables malignant cells to evade immune surveillance and promoting tumor growth and metastasis." (PMID 38779660, 2024). "However, since elevated CXCL12 levels could enhance B cell migration, systemic administration of exogenous CXCL12 might partially counteract the chemotactic effect of tumor‐secreted CXCL12." (PMID 39422063, 2024). "However, no study has elucidated the specific molecular mechanisms by which the CXCL12/CXCR4/ACKR3 axis activates the JAK2/STAT3 pathway, and responses to the CXCL12/STAT3 signal transduction may vary across different tumor types and cell lines." (PMID 38920657, 2024). "Matrix cell-derived CXCL-12 could promote macrophages’ migratory movement across the inner-endothelial barrier and contribute to the aggregation and survival of TAMs in hypoxic areas of the tumor." (PMID 39065562, 2024). "The high expression of MCP-1 and CXCL12 in tumor-bearing mice could enrich MDSCs to the tumor site." (PMID 38641823, 2024). "The question remains why, in the xenograft tumor model, the MDMX-associated upregulation of CXCR4 was a result of an increase in mRNA and protein, and why, in this exogenous model of the addition of CXCL12, the only increase observed was in the CXCR4 protein levels." (PMID 39766093, 2024).
tumor (continued). "Interestingly, both CD8+ T and NK cells were also in close proximity to the CXCL12+ACTA2+ tumor area in high-stromal samples, which suggested that CXCL12 could keep CD8+ T and NK cells from trafficking into the tumor islets." (PMID 38182756, 2024). "Therefore, inhibition of CXCR4/CXCL12 or Tie2 kinase may serve as a target to prevent tumor intravasation." (PMID 39003350, 2024). "Additionally, SOX9‐AS1 might influence the secretion of chemokines such as CCL2 and CXCL12, which recruit immunosuppressive cells like regulatory T cells (Tregs) and myeloid‐derived suppressor cells (MDSCs), further inhibiting anti‐tumour immune responses." (PMID 39550706, 2024). "During tumour progression, TAMs may be more inclined to the M2 polarized state and can secrete various growth factors such as VEGF, PDGF, EGF, chemokines and cytokines such as IL-10, TGF-β, CCL2 and CXCL12; thus, the tissue trophic function of M2-type TAMs instead promotes tumour progression." (PMID 39060648, 2024). "Therefore, CXCL12 secreted by CAFs can promote tumour progression." (PMID 38766687, 2024). "Therefore, leveraging CXCR4 expression on metastatic cells, we propose that the development of an injectable gel containing CXCL12 could regulate tumor cell migration direction, preventing their escape to distant sites." (PMID 39771496, 2024). "Notably, among these pro‐tumor factors, we found two secreted chemokine genes, Cxcl1 and Cxcl12, were consistently down‐regulated in the Mg‐CaCO3 group (relative expression level of group V: Cxcl1: 0.1757, Cxcl12: 0.1154)." (PMID 38757665, 2024). "Thus, activation of the CXCL12/CXCR4/MAPK pathway is important for tumour growth and metastasis." (PMID 38766687, 2024). "Increased levels of CXCL12 promote the accumulation and amplification of myeloid-derived suppressor cells, M2-phenotype macrophages, and regulatory T cells, which contributes to the induction of an immunosuppressive/anergic tumor-permissive environment to benefit tumor formation in TNBC." (PMID 38971778, 2024). "Tumour infiltrating immune cells including T cells can also be affected by cancer-associated fibroblasts that can promote tumour growth and prevent and polarize T-cell function through the release of cytokines and chemokines such as TGFβ, IL6, indoleamine 2,3-dioxygenase (IDO), and CXCL12." (PMID 38567060, 2023). "Moreover, muscle cells adjacent to tumor cells often exhibited abundant CXCL12 expression." (PMID 36300800, 2023). "However, besides myofibroblasts, we further identified the other two branches of differentiation for CAF and revealed that the number of CXCL12+ CAF was increased during tumor progression and became more fibrotic based on the expression of transcription factor JUN." (PMID 37360193, 2023). "Since CXCL12 has also been associated with fibroblast-induced tumor cell migration, we assessed whether CD26+ NF-derived CXCL12 was also responsible for the observed invasion of tumor cells in the organotypic invasion assays." (PMID 36635273, 2023). "In addition, CAFs establish immune crosstalk by secreting chemokines and cytokines such as IL-6, TGF-β, and CXCL12, thereby interfering with T cell function and recruiting myeloid-derived suppressor cells (MDSC), regulatory T cells (Treg) and tumor-associated macrophage (TAM)." (PMID 37046312, 2023). "Expression of the chemokines Cxcl7 and Ccl5 was significantly elevated, and Cxcl2 and Cxcl12 trended upward in H1792ΔSTK11 tumors compared with control tumors when using mouse primers, concordant with the observed changes in tumor immune cellularity and consistent with host responses." (PMID 37092555, 2023). "Therefore, CXCR4+ tumour cells tend to metastasize to organs that express CXCL12 via blood vessels." (PMID 37162544, 2023). "However, the predominant tumor-promoting effects of CXCL12 are tightly regulated." (PMID 36725964, 2023).
tumor (continued). "Therefore, in this study, we focused on CXCL12 and investigated whether the expression of CXCL12 by tumor cells and cancer-associated fibroblasts is associated with the prognosis of NSCLC patients undergoing complete tumor resection." (PMID 37227446, 2023). "Thus, the development of an efficient and tunable CXCL12 delivery system could represent a promising therapeutic strategy to be injected into a hydrogel employed to fill a cavity after surgical tumor resection." (PMID 36980182, 2023). "By studying a model of spontaneous lung metastasis induced by the tumor cell line 4T1, investigators also discovered that CXCR4 was expressed on tumor-draining lymph node B cells, which could attract CXCL12-producing 4T1 cells and kill tumor cells by the perforin pathway." (PMID 37215990, 2023). "In addition, although intercellular communication between tumour cells and the CXCL12/CXCR4 signalling pathway has been widely studied in tumour chemotactic and metastatic processes in many cancer types, few studies have focused on the effect of NPM1 in CXCL12-mediated HCC chemotaxis and migration." (PMID 37251542, 2023). "Blocking CXCL12’s effect on PDAC cells may improve anti-tumour immunity." (PMID 36284087, 2022). "Additionally, it has also been shown that CAFs may directly stimulate tumor angiogenesis via paracrine CXCL12 signaling in GC." (PMID 36244987, 2022). "The activation of macrophage phagocytosis of tumor cells and co-presentation of their antigens may synergize with the chemoattractant activity of CXCL12 towards monocytes and macrophages, with CXCR4-TCR co-signaling in the immune synapse and with BCR co-signaling in mature B cells." (PMID 35565443, 2022). "In addition, TGF-β can also generate myofibroblasts in the peritumoural stroma from stromal precursor cells, called tumour-associated myofibroblasts, which facilitate tumour development by their ability to produce matrix metalloproteinases, cytokines (IL8) or chemokines (CXCL12)." (PMID 35954497, 2022). "One hypothesis is that before metastasis develops, many CRC cells undergo DNA hypermethylation on the CXCL12 promoter, such that autocrine and paracrine CXCL12 signaling is reduced and tumor cells can migrate along a gradient that leads them to distant organs, known to highly express the chemokine." (PMID 35406582, 2022). "Importantly, the blocking of CXCL12/CXCR4 axis inhibits tumor growth and impairs metastasis." (PMID 35155581, 2022). "In addition, pretreatment of AsPC-1 cells with BsNb PX4 or Nb CXCR4 resulted in a negative impact on cell proliferation, which indicated that the inhibitory effect of BsNb PX4 on tumour cells might involve blocking the CXCL12/CXCR4 signalling pathway." (PMID 36284271, 2022). "Conceivably, 7HP349 therapy, which increases CD8+ Teff recruitment to the TME in cooperation with neutrophils in a CXCL12-dependent manner, could trigger efficient tumor infiltration by CD8+ Teffs and increase the percentage of cancer patients who experience a response to immunotherapy." (PMID 35552271, 2022). "CXCL12 may influence cancer cell proliferation, apoptosis inhibition, neovascularization, EMT, and recruitment of tumor-associated macrophages (TAMs) in the tumor microenvironment." (PMID 35408440, 2022). "On the basis of these findings, we propose that the tumor stroma represents a myeloid cell–enriched microenvironment with abundant expression of CXCL12, which upon LFA-1 activation by 7HP349, could enhance recruitment and stabilize CD8+ Teffs at the immunologic synapse." (PMID 35552271, 2022). "In addition, CXCL12 expression, especially in tumor cell membrane, was correlated with metastasis." (PMID 35729596, 2022). "Notably, tumor arterial EC expressed CXCL12 the highest, even among angiogenic phenotypes." (PMID 35717322, 2022). "In tumor microenvironment, CXCL12 could be expressed by tumor, immune and stromal cells." (PMID 35729596, 2022).